USP32 (ubiquitin specific peptidase 32)
Description:
Deubiquitinase that can remove conjugated ubiquitin from target proteins, such as RAB7A and LAMTOR1. Acts as a positive regulator of the mTORC1 signaling by mediating deubiquitination of LAMTOR1, thereby promoting the association between LAMTOR1 and the lysosomal V-ATPase complex and subsequent activation of the mTORC1 complex.
Synonyms: USP10; NY-REN-60
Tractability: PROTAC: ubiquitination databases record sites on it; its protein half-life has been measured.
Target class: Enzyme; Hydrolase
Chemical probes: Huib32 (high quality)
Gene: Protein-coding gene on chromosome 17 (60,177,327 to 60,422,470, reverse strand). Ensembl gene ENSG00000170832.
Subcellular location: Golgi apparatus membrane
Subcellular location (Human Protein Atlas): Golgi apparatus; Cytosol
Gene Ontology:
Molecular function: cysteine-type deubiquitinase activity; protein binding; calcium ion binding
Biological process: positive regulation of TORC1 signaling; protein deubiquitination
Cellular component: Golgi apparatus; Golgi membrane; cytoplasm; endomembrane system
Genetic constraint (gnomAD): Loss-of-function variants: 52 observed, 175.15 expected, observed/expected ratio (o/e) 0.3, 90% interval 0.24 to 0.37. The synonymous counts are far from expectation, so gnomAD's model fits this gene poorly and the ratio says little. Missense variants: 1,054 observed, 1,777.1 expected, observed/expected ratio (o/e) 0.59, 90% interval 0.56 to 0.62. Synonymous variants: 473 observed, 628.38 expected, observed/expected ratio (o/e) 0.75, 90% interval 0.7 to 0.81.
Homologues: Orthologues: macaque USP32 (99% identical), dog USP32 (97% identical), mouse Usp32 (96% identical), rat Usp32 (95% identical), tropical clawed frog usp32 (83% identical), zebrafish usp32 (77% identical), chimpanzee USP32 (34% identical). Paralogues in human: USP6 (61% identical), USP15 (17% identical), USP4 (16% identical), USP11 (16% identical), USP19 (16% identical), USP24 (14% identical), USP9X (14% identical), USP8 (13% identical), USP9Y (13% identical), USP31 (12% identical), USP43 (12% identical), USP38 (10% identical), and 59 more.
Diseases named in the same sentence as USP32 in open-access papers:
USP32 is named in the same sentence as 40 diseases in open-access papers, as found by Europe PMC text mining. Sharing a sentence is not in itself a finding about the gene and the disease. The quoted sentences say what the papers report.
breast carcinoma (13 papers, 2012 to 2026). "For an instance, USP32 facilitates tumor immune escape in hepatocellular carcinoma 39, which is associated with the advancement of small cell lung cancer 40, breast cancer 41, glioblastoma 42, gastric cancer, and epithelial ovarian cancer." (PMID 41356798, 2026). "Overall, our DUB-screening strategy revealed a resistance mechanism governed by USP32 associated with YM155 resistance in breast cancers, one that presents an attractive molecular target for anti-cancer therapies." (PMID 34815782, 2021). "USP32, a member of the ubiquitin-specific proteases family, has been implicated in the development of breast cancer and small lung cancer." (PMID 32226309, 2020). "Moreover, USP32 control over the stability of the SLC35F2 protein is linked to YM155 resistance in breast cancer." (PMID 39030175, 2024). "USP32 has reportedly been linked to the medication resistance mechanism in breast cancer." (PMID 37679322, 2023). "USP32 also contributes to the development of YM155 drug resistance in breast cancers by downregulating SLC35F2 protein expression." (PMID 41356798, 2026). "In one work, USP32 transcript analysis was expanded to breast cancer cell lines and primary tumors in order to examine USP32 expression in breast cancer cells." (PMID 37679322, 2023). "As a result, miR let-7a can regulate USP32 in BCa, which can decrease proliferation and offer a new potential target for the treatment of breast cancer." (PMID 37679322, 2023). "USP32 was discovered to be overexpressed in both primary breast tumors and breast cancer cell lines." (PMID 37679322, 2023). "USP32 is upregulated in a variety of cancers, including small cell lung cancer, gastric cancer, breast cancer, epithelial ovarian cancer, glioblastoma, gastrointestinal stromal tumor, pancreatic duct adenocarcinoma and acute myeloid leukemia." (PMID 37679322, 2023). "USP32 was highly upregulated in breast cancer while SLC35F2 were significantly lower in these tissues." (PMID 34815782, 2021). "In summary, USP32 knockout sensitized breast cancer cells to YM155-mediated DNA damage and promoted cell apoptosis by inhibiting the PI3K/AKT/mTOR pathway and survivin protein level." (PMID 34815782, 2021). "High USP32 transcript levels were also reported in 50% (nine of 18) of breast cancer cell lines and 22% (nine of 41) of primary breast tumors compared with mammary epithelial cells." (PMID 25606592, 2014). "USP32 was found to have an elevated copy number in estrogen receptor (ER) positive tumors, which is one of the 81 gene copy number traits that predict the metastatic capacity of breast cancer." (PMID 37679322, 2023). "USP32 belongs to the ubiquitin-specific protease family, deubiquitinating enzymes which have been reported to be involved in several cancer initiation and progression (ovarian cancer, gastric cancer, glioblastoma, breast cancer, small cell lung cancer)." (PMID 37587471, 2023). "USP32 is overexpressed in breast cancer and human small cell lung cancer and may serve as an oncogene through promoting cell proliferation and tumor metastasis." (PMID 35906355, 2022). "In fact, USP32 exhibits overexpressed in breast cancer and human small cell lung cancer and may serve as an oncogene through promoting cell proliferation and tumor metastasis 18,19." (PMID 32226309, 2020). "The USP32 gene localizes on chromosome 17q23, which is commonly amplified in breast cancer." (PMID 25606592, 2014). "Meanwhile, it has been noted that USP32 is one of the transcripts that are up-regulated in malignant breast epithelial cells, indicating that USP32 may be a helpful biomarker in a subclass of breast cancer cells." (PMID 37679322, 2023). "USP32 was found to be overexpressed more than twofold in 9 of 18 breast cancer cell lines compared to normal breast tissue, and upregulation of USP32 in mammary epithelial cells may be important in pathogenesis of breast cancer and/or serve as a useful biomarker in breast cancer cells." (PMID 27506935, 2016).
breast carcinoma (continued). "The ubiquitin-specific peptidase 32 (USP32), a member of the USP family of DUBs, is a membrane-bound deubiquitinating enzyme, which was first discovered to act as an oncogene in breast cancer." (PMID 40136417, 2025). "USP32 is a poorly characterized DUB family member and was identified previously as a membrane-bound protease overexpressed in breast cancers." (PMID 34815782, 2021). "Therefore, inhibition of USP32 can increase the protein expression of SLC35F2 and improve the chemotherapeutic effect of YM155 on breast cancer, opening up a new pathway for clinical drug resistance treatment." (PMID 37679322, 2023). "Researchers further found that the direct binding of USP32 and SLC35F2 in the endoplasmic reticulum could negatively regulate the stability of SLC35F2 and promote drug resistance to YM155 in breast cancer cells." (PMID 37679322, 2023). "Several of the fused genes are also recurrently broken in a substantial proportion of breast cancers, as judged by copy number steps in array-CGH of 1000 breast tumours: around 10% have breaks in ERBB2, BCAS3 and SKAP1, while COL14A1, TIAM1, USP32, TAOK1 are broken in around 4%." (PMID 23260012, 2012). "17, a region which included three genes: USP32 (ubiquitin specific peptidase 32), known to be overexpressed in breast cancer and colorectal metastatic disease, C17orf64 (an open reading frame) and APPBP2 (amyloid beta precursor protein binding protein 2), also highly expressed in breast cancer." (PMID 31795195, 2019).
gastric cancer (11 papers, 2020 to 2026). A primary or metastatic malignant neoplasm involving the stomach. "The silencing of USP32 has been shown to suppress gastric cancer tumorigenesis through the modulation of SMAD2 expression." (PMID 41356798, 2026). "USP32 overexpression in gastric cancer (GC) enhances SMAD2 deubiquitination, correlating with advanced tumor stages, increased cisplatin resistance, and poorer survival." (PMID 38702734, 2024). "For example, USP32 influences the invasion, migration, and proliferation of small cell lung cancer; USP32 affects the development of epithelial ovarian cancer, glioblastoma, and gastric cancer through the regulation of related proteins." (PMID 39030175, 2024). "The researchers also found that after the silencing of USP32 expression in gastric cancer, the expression of SHMT2 decreased." (PMID 37679322, 2023). "Another study found that early and late stages of gastric cancer had higher expression levels of the USP32 and SHMT2 proteins, and immunohistochemistry analysis supported these findings." (PMID 37679322, 2023). "USP32 is highly expressed in gastric cancer and is closely related to the high T‐staging and poor prognosis of gastric cancer patients." (PMID 37143582, 2023). "Gastric cancer cells’ cisplatin resistance can be decreased by down-regulating USP32 expression, indicating that USP32 is involved in the development of cisplatin resistance." (PMID 37679322, 2023). "The strong staining of USP32 was far more frequently observed in gastric cancer tissues (197/314, 62.7%) than in para-carcinoma normal tissues (5/22, 22.7%)." (PMID 32226309, 2020). "To explore the expression pattern of USP32 in GC, we performed an immunohistochemical (IHC) analysis using USP32 specific antibody in a human gastric cancer tissue microarray, which contains 314 tumor samples and 22 non-tumor tissues." (PMID 32226309, 2020). "Inhibiting USP32 can help overcome cisplatin resistance in gastric cancer cells." (PMID 39605891, 2024). "USP32 enhances gastric cancer growth and drug resistance by increasing SMAD2 levels." (PMID 39605891, 2024). "It is more likely that USP32 will be used as a possible biomarker and therapeutic target for gastric cancer because of the high expression of USP32 in this disease and its relationship to the short overall survival rate and high T stage of gastric cancer patients." (PMID 37679322, 2023). "Meanwhile, rescue experiments showed that overexpression of SMAD2 could reverse the effects of silenced USP32 on gastric cancer cell growth, metastasis and cisplatin resistance." (PMID 37679322, 2023). "Moreover, we also found that USP32 is upregulated in gastric cancer tissues and its expression has strong clinical relevance." (PMID 32226309, 2020). "It has been found that USP32 is abundantly expressed in gastric cancer and that it regulates chemoresistance in GC and SMAD2 cells." (PMID 39030175, 2024). "However, little is known about the function and expression of USP32 in gastric cancer." (PMID 32226309, 2020). "Downregulation of USP32 can significantly inhibit the expression of SMAD2, thereby inhibiting the proliferation, migration, and chemoresistance to cisplatin of gastric cancer cells." (PMID 37143582, 2023). "In gastric cancer, ubiquitin-related enzymes such as TRIM22 and USP32 promote the proliferation and invasion of gastric cancer cells by affecting the stability of the SMAD2 protein, which is highly expressed in gastric cancer." (PMID 37685308, 2023).
small cell lung carcinoma (7 papers, 2021 to 2026). Small cell lung cancer (SCLC) is a highly aggressive malignant neoplasm, accounting for 10-15% of lung cancer cases, characterized byrapid growth, and early metastasis. "A previous study has found that there are correlations of USP32 expression with clinicopathologic features in small cell lung cancer." (PMID 37957631, 2023). "It is interesting to note that USP32 can influence the development of small-cell lung cancer’s cell cycle." (PMID 37679322, 2023). "According to a study, USP32 is highly expressed in small-cell lung cancer." (PMID 37679322, 2023). "For small-cell lung cancer, USP32 is thought to be a potential therapeutic target." (PMID 37679322, 2023). "Thus, the ability of small cell lung cancer cells to proliferate and generate clones, as well as the ability of cells to invade and migrate, could be inhibited by interfering with USP32." (PMID 37679322, 2023).
glioblastoma (5 papers, 2022 to 2026). The most malignant astrocytic tumor (WHO grade IV). "Glioblastoma cell lines (Umur118 MG, Umur87 MG, A172, T98G, and Umur251 MG) had higher mRNA and protein levels of USP32 than normal brain cells SVG p12." (PMID 37679322, 2023). "Therefore, USP32 is a promising new molecular target, from which researchers can study new treatments to control the development of glioblastoma." (PMID 37679322, 2023). "Unexpectedly, glioblastoma has a low expression level of USP32 in the TCGA database." (PMID 37679322, 2023). "Thus, we need to learn more about USP32 expression in glioblastoma and its function." (PMID 37679322, 2023). "However, in four additional tumor samples-glioblastoma multiforme (GBM), kidney suspicious cell (KICH), thyroid cancer (THCA), and endometrial cancer (UCEC)-USP32 gene expression were dramatically downregulated." (PMID 37679322, 2023).
breast tumors (4 papers, 2007 to 2021). "USP32 was also found overexpressed in BC cell lines and primary breast tumors, suggesting its role as a therapeutic and prognostic target in ERα-positive BC." (PMID 33535487, 2021). "The interest in USP32 as a therapeutic target was generated following the study of Zhang and colleagues, which identified USP32 as the prognostic gene with copy number alterations in estrogen receptor-positive human breast tumors." (PMID 25606592, 2014). "Finally, our data revealed seven other protein coding genes (FAM33A, DHX40, CLTC, PTRH2, TMEM49, TUBD1, ABC1, and USP32) that have not been implicated previously in 17q23 studies, but whose expression was clearly associated with copy number status in primary breast tumours." (PMID 17353917, 2007).
epithelial ovarian cancer (4 papers, 2022 to 2026). "Epithelial ovarian cancer has a bad prognosis, which is directly associated with USP32." (PMID 37679322, 2023). "In one study, the researchers used the pertinent database search to discover that USP32 was substantially expressed in human ovarian cancer peritoneal tumors and was regulated in ovarian cancer." (PMID 37679322, 2023). "They showed that USP32 and FDFT1 expression was higher in tumor spheroids than in adnexal cells, and that the FDFT1 inhibitor ZA, blocking USP32, or interfering with the mevalonate pathway might inhibit the formation of tumor spheres in epithelial ovarian cancer." (PMID 37679322, 2023).
hepatocellular carcinoma (4 papers, 2023 to 2026). A malignant tumor that arises from hepatocytes. "USP32 shows high expression in hepatocellular carcinoma and is closely associated with HCC development and immunotherapy." (PMID 39030175, 2024). "Among them, six types of cancer, including cholangiocarcinoma, esophageal cancer, head and neck squamous cell carcinoma, hepatocellular carcinoma, and gastric adenocarcinoma, show elevated USP32 mRNA expression levels." (PMID 40607251, 2025).
non-small cell lung carcinoma (3 papers, 2024 to 2026). A group of at least three distinct histological types of lung cancer, including non-small cell squamous cell carcinoma, adenocarcinoma, and large cell carcinoma. "Notably, other USP family members—including USP22, USP10, and USP32—have been associated with adverse prognosis in various malignancies, including pancreatic ductal adenocarcinoma, non-small cell lung cancer." (PMID 40926837, 2025). "Overall, our work reveals USP32 as a potential therapeutic target for patients with non-small cell lung cancer and complements the deubiquitination regulatory network of BAG3." (PMID 39030175, 2024). "The regulatory significance of ubiquitin-specific peptidase 32 (USP32) in tumor is significant, nevertheless, the biological roles and regulatory mechanisms of USP32 in non-small cell lung cancer (NSCLC) remain unclear." (PMID 39030175, 2024). "Target proteins that may facilitate the promotion of USP32 for the development of non-small cell lung cancer were identified using isobaric tags for relative and absolute quantitation (iTRAQ), which was utilized to look into possible deubiquitination substrates for USP32." (PMID 39030175, 2024). "The mechanism of action of USP32 in non-small cell lung cancer is currently unknown." (PMID 39030175, 2024). "Together, our data suggested that USP32 may be a tumorigenic factor in non-small cell lung cancer." (PMID 39030175, 2024). "After that, USP32 and BAG3 were tested in non-small cell lung cancer cell lines in order to experimentally validate their protein levels." (PMID 39030175, 2024). "The findings demonstrated a favorable correlation between USP32 and BAG3 expression in a variety of non-small cell lung cancer cell lines." (PMID 39030175, 2024). "Recent report suggest that USP32 promotes tumor progression by activating the RAF/MEK/ERK signaling pathway and inducing epithelial-mesenchymal transition (EMT) by stabilizing BAG3 protein expression in non-small cell lung cancer." (PMID 41356798, 2026).
acute myeloid leukemia (2 papers, 2023 to 2025). Acute myeloid leukemia (AML) is a group of neoplasms arising from precursor cells committed to the myeloid cell-line differentiation. "USP32 promotes the malignant behaviors of acute myeloid leukemia cells by regulating the stability of Rap1b." (PMID 40136417, 2025). "A study reveals the regulatory mechanisms of USP32 and circRNAs in acute myeloid leukemia." (PMID 37679322, 2023).
colorectal cancer (2 papers, 2025 to 2026). A primary or metastatic malignant neoplasm that affects the colon or rectum. "In this study, we examined PD-L1 expression in various types of immune cells in human colorectal cancer in connection to cancer progression-specific USPs, including USP10, USP12, USP14, USP18, USP32, USP33, and USP39." (PMID 41356798, 2026).
pancreatic ductal adenocarcinoma (2 papers, 2023 to 2025). An infiltrating adenocarcinoma that arises from the epithelial cells of the pancreas. "A recent work suggests a pivotal role of USP32 in pancreatic ductal adenocarcinoma given its higher expression levels compared to normal pancreatic tissues and a significant association with tumor grade and stage." (PMID 37587471, 2023).
asthma (1 paper, 2025).
basal cell carcinoma (1 paper, 2025). A carcinoma involving the basal cells. "USP32 was enriched in KEGG pathways including basal cell carcinoma, cardiac muscle contraction, focal adhesion, maturation-onset diabetes of the young, and Wnt signaling pathway." (PMID 40924716, 2025).
cholangiocarcinoma (1 paper, 2023). A carcinoma that arises from the intrahepatic biliary tree (intrahepatic cholangiocarcinoma) or from the junction, or adjacent to the junction, of the right and left hepatic ducts (hilar cholangiocarcinoma). "In terms of statistical significance, six of them, including cholangiocarcinoma (CHOL), esophageal carcinoma (ESCA), head and neck squamous cell carcinoma (HNSC), hepatocellular carcinoma (LIHC), and stomach adenocarcinoma (STAD), displayed increased levels of USP32 mRNA expression." (PMID 37679322, 2023).